IGF1 (insulin like growth factor 1)
Diseases named in the same sentence as IGF1 in open-access papers (continued):
Sharing a sentence is not in itself a finding about the gene and the disease.
prostate carcinoma (continued). "Studies described herein have addressed whether IGF-1 has a direct effect on the invasive potential of DU145 prostate carcinoma cells and have established some of the mechanisms involved." (PMID 18598360, 2008). "For example, EGF, transforming growth factor α, insulin-like growth factor 1, interleukin 6, keratinocyte growth factor, and other fibroblast growth factor family members are expressed in advanced prostate cancers and are believed to be important in fueling androgen-independent growth." (PMID 17384772, 2007). "The evidence in humans is less clear regarding whether an altered endocrine environment can cause prostate tumors although numerous studies link elevated levels of IGF-1 with prostate cancer." (PMID 17805427, 2007). "Similarly, in prostate cancer, butyrate enhances proliferation via IGF-1 signalling." (PMID 40925904, 2025). "Inflammation is associated with increased levels of IGF-1, which is a known potent mitogen for androgen-sensitive and androgen-independent prostate cancer, leading to dysregulation of the PI3K/Akt/mTOR pathway, which plays a key role in the pathogenesis of prostate cancer." (PMID 39954205, 2025). "Similarly, another study on SCFA and prostate carcinogenesis noted that high - fat diet and antibiotic application affect SCFAs by interfering with the GM, and SCFAs can stimulate the level of insulin - like growth factor - 1 (IGF1) to promote the proliferation of prostate cancer cells." (PMID 39703512, 2024). "The possible relation between MS and prostate cancer has been proposed to be an increase in sympathetic activity, which drives prostate gland growth, and a dysregulation in the production of specific cytokines, IGF-1, which disrupts the prostate’s normal functioning." (PMID 37036830, 2023). "In prostate cancer, a high lipid diet may accelerate tumor cell proliferation by increasing levels of insulin-like growth factor 1, IL-1α, IL-1β, IL -6, or TNF-α or through activation of signaling pathways such as MCP-1/CCR2 (monocyte chemoattractant protein-1/C-C Motif Chemokine Receptor 2)." (PMID 38028534, 2023). "Moreover, colocalization analyses showed strong evidence of a shared genetic cause at the IGF1 gene for IGF-I concentrations and risk for prostate cancer, indicating that our findings are unlikely to be due to confounding by linkage disequilibrium." (PMID 35726641, 2023). "In prostate cancer, where androgen deprivation causes prostate carcinoma and stromal cells to upregulate the IGFBP5 level, overexpression of IGFBP5 enhances the anti-apoptotic and mitogenic activity of recombinant IGF1 protein, thereby helping to overcome castration-induced tumor regression." (PMID 36093095, 2022). "Therefore, further investigation of co-targeting reciprocal interactions of AR and IGF1 pathways between epithelial tumor cells and surrounding tumor niches may provide insight into potential therapeutic strategies for treating advanced prostate cancer." (PMID 36323713, 2022). "Therefore, further investigation of therapeutic strategies by co-targeting reciprocal interactions of AR and IGF1 pathways between epithelial tumor cells and surrounding tumor niches may improve clinical outcomes for advanced prostate cancer." (PMID 36323713, 2022). "Moreover, both insulin and IGF-1 signalling could play an essential role in driving prostate cancer growth." (PMID 33816477, 2021). "Hence, more research is necessary to clarify whether IGF‐1 plays a role in the development of advanced stage prostate cancer." (PMID 32717139, 2020). "A recent Mendelian randomization study showed that genetically predicted insulin-like growth factor 1 levels were significantly positively associated with prostate cancer in the UK Biobank and non-significantly positively associated with prostate cancer in the PRACTICAL consortium and BioBank Japan." (PMID 33261611, 2020).
prostate carcinoma (continued). "Similarly, other members of the Erb family that are capable of forming heterodimers with EGFR or posttranslational modifications and overexpression of other cell surface receptors, including IGF-1, identified in our proteomics data have been shown to play anti-apoptotic roles in prostate cancer." (PMID 32085441, 2020). "It is also possible that studies reporting associations of dairy products with subsequent prostate cancer risk may reflect the mediating role of proteins and growth factors (e.g. insulin-like growth factor 1) in prostate carcinogenesis, and not calcium per se." (PMID 30306355, 2018). "Also, it is reported that upregulation of PI3K/AKT, Wnt/B-catenin and IGF1 signaling pathways may contribute to activation of AR signaling and aggressiveness in African-American prostate cancer." (PMID 28039468, 2017). "The levels of IGF-1 is high in androgen-independent prostate cancer, suggesting that this growth factor might serve as an alternate to androgens in mediating Akt activation and high miR-21 expression in this type of prostate cancer." (PMID 23272133, 2012). "Some limited in vitro evidence suggests a direct link between the IGF-1/insulin axes and vitamin D. For example, laboratory studies on cultured the human prostate cancer cells the LNCaP human prostate cancer cell line have suggested that 1,25-dihydroxyvitamin D3 might influence IGFBP-3 levels." (PMID 22216097, 2011). "Catechins are reported to inhibit prostate cancer growth, induce intrinsic and extrinsic apoptotic pathways, decrease inflammation by inhibiting COX-2 levels and IGF-1-related signalling, and exert antioxidant properties." (PMID 39954205, 2025). "Additionally, lycopene could alleviate the prostate cancer risk by modulating the growth genes like cyclin-dependent protein kinase 7 (CDK7), B-cell lymphoma 2 (BCL2), epidermal growth factor receptor (EGFR), and insulin-like growth factor 1 (IGF-1) receptor." (PMID 40013157, 2025). "To investigate how IGF-1 contributes to PD-L1 regulation, we tested effects of inhibiting signaling pathways of IGF-1R and it’s downstream effectors MEK-ERK and AKT in DU145 prostate cancer cells." (PMID 41184420, 2025). "SCFAs can stimulate systemic and local prostatic insulin-like growth factor 1 (IGF-1), thereby activating downstream signaling pathways in prostate cancer cells and promoting tumor effect." (PMID 41375042, 2025). "BMI: body mass index, HDL: high-density lipoprotein, PSA: prostate-specific antigen, IGF-1: insulin-like growth factor-1, BPH: benign prostatic hyperplasia, PCA: prostate cancer." (PMID 39781138, 2024). "BMI: body mass index, HDL: high-density lipoprotein, PSA: prostate-specific antigen, IGF-1: insulin-like growth factor-1, PCA: prostate cancer, BPH: benign prostatic hyperplasia." (PMID 39781138, 2024). "SCFAs can promote the production of insulin growth factor 1 (IGF-1) in the whole body and the prostate, and IGF-1 can activate the proliferation of prostate cancer cells through the MAPK and PI3K pathways." (PMID 37764869, 2023). "For example, in the bone microenvironment, prostate cancer cells secret bone-related soluble factors such as RANKL and M-CSF to activate osteoclasts; and osteoclasts in turn release TGF-β and IGF-1 to support the growth of prostate cancer cells." (PMID 36810084, 2023). "The present study investigated the influence of IGF-1 on tumor growth and migration properties using androgen-dependent LNCaP and VCaP and androgen-independent PC3 and DU145 prostate cancer cells." (PMID 35053528, 2022). "For instance, IGF1 production stimulated by SCFAs from gut microbes influenced the growth of prostate cancer via activating local prostate MAPK and PI3K signaling, indicating the existence of a gut microbiota–IGF1–prostate axis." (PMID 36360204, 2022). "IGF-1 driven cross-communication between Akt/mTOR and FAK-integrin signaling has been demonstrated in the androgen-resistant prostate cancer cell lines DU145 and PC3." (PMID 35053528, 2022).
prostate carcinoma (continued). "Multiple lines of evidence have shown that IGF1 signaling directly induces and promotes PIN development in both mouse prostate cancer models and human prostate cancers." (PMID 35902588, 2022). "Through the adenosine monophosphate-activated protein kinase (AMPK)-dependent suppression of androgen signaling pathway and insulin-like growth factor-1 (IGF-1), metformin inhibits proliferation of prostate cancer." (PMID 34055551, 2021). "It was also observed that both IGF-1 and IL-6 can induce the phosphorylation of AKT at Ser-473 and PKCα at Ser-657 in prostate cancer cells in the present study." (PMID 34682865, 2021). "Various survival pathways have been reported to participate in prostate cancer growth in the bone niche, including PTHrP, TGF-β, IGF-1, FGF-2, IL-6 as well as ET-1 signaling." (PMID 34831167, 2021). "For example, prostate cancer cells secrete BMPs, TGF-β, IGF-1, PDGF, endothelin-1 (ET-1), VEGF and micro-RNA (miR)-940, which promote osteoblast differentiation and activation." (PMID 34831167, 2021). "During this phase, prostate cancer cells induce a dysfunctional osteoblastic phenotype, through the production of factors including BMPs, TGF-β, PDGF, adrenomedullin, IGF-1, FGF, and vascular endothelial growth factor (VEGF)." (PMID 32640686, 2020). "In addition, concerns have been raised that if circulatory IGF-1 is raised in response to colostrum supplementation, prolonged administration of colostrum might stimulate malignancy in distant organs such as prostate cancer which is known to commonly express IGF-1 receptors." (PMID 31123862, 2020). "Growing evidence indicates that IGF1/IGF1R is found highly expressing in multiple types of cancer such as colorectal cancer, non‐small cell lung cancer, prostate cancer, and gastrointestinal stromal tumors." (PMID 32851683, 2020). "Bone metastatic prostate cancer cells secrete factors that promote osteoblast differentiation, including bone morphogenic proteins (BMPs), TGF-beta, IGF-1, platelet-derived growth factor, endothelin-1, and VEGF." (PMID 29867053, 2018). "For example, several osteoblast-stimulating factors such as bone morphogenetic proteins (BMPs), insulin-like growth factor-1 (IGF-1), and transforming growth factor-β (TGF-β) have been detected in prostate cancer cells." (PMID 28303941, 2017). "In the case of human prostate cancer cell lines (PC3 and LNCaP), 24‐hrs treatment with IGF1 and insulin reduced (or tended to reduce) the expression of IGF1R, INSR and GHR, whereas only insulin increased the expression levels of Igfbp3 in LNCaP cells." (PMID 28244645, 2017). "Dietary-induced hyperinsulinemia via excessive consumption of carbohydrate food sources has been shown to increase levels of IGF-1 and activate the insulin pathway and AKT, increasing prostate cancer growth in mouse studies." (PMID 26977321, 2016). "Insulin and IGF1 enhance IL-17-induced inflammatory responses through suppressing GSK3, leading to enhanced prostate cancer formation in obese mice." (PMID 26871944, 2016). "The primary outcome of the study is a change in prostate cancer relevant cytokines and hormones (IL-6, MIF, IGF-1, Testosterone)." (PMID 23731674, 2013). "The data indicates a regulatory role of IGF-1 signalling via both the PI3-K and MAPK pathways in DU145 prostate carcinoma cells." (PMID 18598360, 2008). "Luteolin inhibited insulin-like growth factor -1 (IGF-1)- induced activation of IGF-1R and Akt in prostate cancer PC-3 and DU145 cells." (PMID 18946424, 2008). "Systemic insulin, IGF-1 and other biomolecules (e.g., HIF-1, VEGF, etc.)may modify ADSCs homeostasis within PPAT, with further effects on prostate cancer biology." (PMID 39941741, 2025).
prostate carcinoma (continued). "Baseline PD-L1 surface expression in both Myc-CaP and 22Rv1 prostate cancer cells was low, and IGF-1 stimulation did not result in a clear increase in surface PD-L1 levels in 22Rv1 cells." (PMID 41184420, 2025). "Prostate cancer DTCs utilise signalling from growth factors such as transforming growth factor beta (TGF-β) and insulin-like growth factor 1 (IGF-1), which are liberated by osteoblastic and osteoclastic remodelling of the bone, to support their proliferation, survival, and subsequent colonisation." (PMID 39796673, 2024). "BMI: body mass index, T.CHO: total cholesterol, TG: triglyceride, HDL: high-density lipoprotein, LDL: low-density lipoprotein, VLDL: very low-density lipoprotein, PSA: prostate-specific antigen, IGF-1: insulin-like growth factor-1, BPH: benign prostatic hyperplasia, PCA: prostate cancer." (PMID 39781138, 2024). "Also, formononetin was reported to induce the early apoptosis of prostate cancer cell DU145 via the regulation of mitochondrial apoptotic pathway and downregulation of IGF-1/IGF-1R signaling pathway." (PMID 38874510, 2024). "Serum insulin and insulin-like growth factor-1 showed non-significant positive correlation, whereas testosterone showed non-significant negative correlation with prostate cancer Gleason score and grade." (PMID 39781138, 2024). "Another study suggested that the expression of HSPB1 may be used to predict poor prognosis and transfer tendency in prostate cancer and demonstrated that HSPB1 was promoted in an insulin-like growth factor 1-dependent manner." (PMID 37268925, 2023). "In a study about lycopene in prostate cancer treatment, the supplementation did not alter the IGF1 and IGFBP3 levels." (PMID 36501182, 2022). "In prostate cancer cells androgens have been shown to upregulate the expression of IGF-1R and as a consequence results in increased proliferation and invasion when stimulated with IGF-1." (PMID 33816477, 2021). "Among these, the CD44—a multifunction cell surface adhesion receptor that is expressed by prostate cancer cells—binds to vascular cell adhesion molecule 1 (VCAM-1), and other factors, including insulin-like growth factor 1 (IGF1), insulin, and interleukin-17 (IL-17) are able to boost this process." (PMID 33535541, 2021). "Chromosomal rearrangements leading to oncogenic fusion like TMPRSS2-ERG, EWS-WT1, and PAX3-FKHR, sustain IGF1R expression in prostate cancer, desmoplastic small cell tumor and alveolar rhabdomyosarcoma, respectively, while EWS-FLI favors IGF1 but inhibits IGFBP3 transcription in Ewing sarcoma." (PMID 34440844, 2021). "In-vitro studies have shown IGFBP-3 to inhibit proliferation, adhesion, invasion and metastasis of prostate cancer, independent of IGF-1." (PMID 32056047, 2020). "However, while PRT has been shown to reduce plasma IGF-1 and increase IGFBP-3 levels in prostate cancer, current epidemiological studies in cancer populations show significant heterogeneity in the response of the systemic IGF axis to exercise." (PMID 32056047, 2020). "Besides, because anticarcinogenic properties of naringenin have been reported in diverse malignant tumors prostate cancer pathway consisting of eight proteins was found: AKT1, MAPK1, IGF1R, AR, CCND1, INS, PIK3CA, IGF1." (PMID 30918758, 2019). "The mean IGF‐1 levels of prostate cancer patients and men with a negative biopsy were 143.8 and 118.9 ng/mL, respectively (P < 0.001)." (PMID 29992746, 2018).
prostate carcinoma (continued). "Evaluation of the altered pathways showed that AR, IGF1, IGFBP5 and ETV1 were markedly decreased in the AfA derived cell line compared with CaA cells, and there was a reciprocal regulatory relationship of miR-24/target expression in prostate cancer patients." (PMID 28157714, 2017). "A more recent meta-analysis of more than 10,000 men with prostate cancer established a positive correlation of IGF-1 and 2 with prostate cancer development, but not progression of metastatic disease." (PMID 27599544, 2016). "Insulin and IGF1 enhanced IL-17-induced inflammatory responses through suppressing GSK3, which was shown in the cultured cell lines in vitro and obese mouse models of prostate cancer in vivo." (PMID 26871944, 2016). "In LNCaP prostate cancer cells, reduced expression of SAM68 altered the expression of an important subset of genes involved in proliferation and apoptosis, including Bcl2L1, Clusterin, cdk2, cdk3, p16INK4, cyclin D1, Par-4, EGF and IGF-1." (PMID 25944080, 2015). "Interestingly, the serum levels of IGF-1, VEGF, and prostate-specific antigen were significantly decreased following the administration of a green tea mixture to prostate cancer patients." (PMID 25789501, 2015). "Since elevated IGF-1 and IGF-1R levels have been associated with many types of cancer and metastases, they cannot be used as prostate cancer markers, at least individually, due to their lack of specificity." (PMID 24877145, 2014). "In a follow-up study, IL-10 blocked IGF-1-induced MMP-2 mRNA expression and protein synthesis in primary prostate cells, implying that regulation of MMP expression in prostate cancer cells is a complex interaction of various cytokines present in the tumor microenvironment." (PMID 24978435, 2014). "Insulin-like growth factor (IGF)-1 was previously shown to up-regulate MMP-2 production in lung cancer, whereas the interleukin (IL)-10/IL-10 receptor axis was found to down-regulate MMP-2 synthesis in prostate cancer cell line PC3 ML." (PMID 24978435, 2014). "A data driven, multivariate approach, was used in this study to predict prostate cancer cell survival based on the phosphorylation levels of key proteins in PC3, LNCaP, and MDA-PCa-2b cell lines in response to EGF, IGF1, IL6, TNFα, dihydrotestosterone, and docetaxel treatment." (PMID 24885093, 2014). "Also, the potential role of IGF1, along with IGFBP3, as prognostic markers that can predict mortality in men with advanced prostate cancer, was reported in a recent clinical study." (PMID 24237932, 2013). "Rising PSA levels during the course of prostate cancer progression may facilitate tumorigenesis by digesting IGFBP3 and releasing free IGF-1 into the prostate microenvironment." (PMID 17453001, 2007). "Serum insulin-like growth factor-1 levels did not correlate with height amongst men with familial or sporadic prostate cancers." (PMID 10638996, 2000). "There was no relation between IGF-1 and BPH, but increased values of this hormone were associated with increased risk of prostate cancer; an increment of 60 ng ml(-1) corresponded to an odds ratio of 1.91 with a 95% confidence interval of 1.00-3.73." (PMID 9365156, 1997). "Additionally, such expression may lead to crosstalk between prostate cancer cells and PPAT by modulatory function on PPAT secretome through the IGF-1 dependent pathway." (PMID 39941741, 2025). "Testing IGF-1-induced expression in this cell line revealed a significant upregulation of PD-L1 surface expression, indicating that the IGF-1–PD-L1 axis is not restricted to prostate cancer but may extend to other malignancies." (PMID 41184420, 2025).